JAK2 (Janus kinase 2)
Diseases named in the same sentence as JAK2 in open-access papers (continued):
Sharing a sentence is not in itself a finding about the gene and the disease.
colon carcinoma (63 papers, 2002 to 2025). "Aberrant activation of JAK2/STAT3 signaling is frequently presented in colon tumors and implicated in the tumor vasculature reprogramming." (PMID 33976735, 2021). "In micro-satellite stable (MSS) colon cancer we observed a similar positive association of JAK2 mutations with NK cell estimates (effect size 1.3, -logP = 1.7)." (PMID 28749946, 2017). "Blocking LIF in a mouse model of colon carcinoma prevented the initiation and progression of cancer cachexia (e.g., muscle wasting) via the Janus kinase 2–signal transducer and activator of transcription 3 (JAK2–STAT3) pathway." (PMID 38887915, 2024). "Our study shows the potential of targeting JAK2 as a novel approach to colon cancer treatment, and demonstrate that ergotamine as a promising effects as an anti-cancer drug." (PMID 38869738, 2024). "It is also verified that miR-34c-5p stimulated cellular proliferation by regulating the SIRT6-mediated activation of the JAK2/STAT3 signaling pathway in colon cancer cells." (PMID 38185635, 2024). "The abnormality in the JAK2/STAT3 pathway is involved in the tumorigenesis of colon cancer including apoptosis." (PMID 38869738, 2024). "The expression and phosphorylation of JAK2 and STAT3 in the tumor tissues were detected by Western blotting to investigate the mechanisms underlying FTGs-mediated inhibition of colon tumor growth." (PMID 38202610, 2023). "Hao and co-workers have shown that hyperexpression of ZNF460 is related to adverse prognosis and that it facilitates cell migration in colon cancer via the JAK2/STAT3 signaling pathway." (PMID 37057209, 2023). "For example, propofol inhibits the development of bladder cancer and colon cancer by regulating miR-145-5p or JAK2/STAT3 signaling pathway." (PMID 37771421, 2023). "After screening for oncogenes or suppressor genes, KIT, KRAS, BRAF, and JAK2 were significantly higher in colon cancer ECs." (PMID 35755820, 2022). "DHA induced the apoptosis of colon cancer cells by targeting janus kinase 2 (JAK2)/signal transducer and activator of transcription 3 (STAT3) signaling." (PMID 33613116, 2021). "Mechanistically, we revealed that ZNF460 promotes the activation of the JAK2/STAT3 signaling pathway in colon cancer cells." (PMID 33976729, 2021). "Mechanistically, we revealed that ZNF460 promotes metastasis through JAK2/STAT3 signaling pathway in colon cancer cells." (PMID 33976729, 2021). "They concluded that PAC exhibits anti-colon cancer properties that have potential, by targeting cyclin D1 and suppressing JAK2/STAT3, AKT/mTOR and MEK/ERK signaling pathways as well as their common downstream effector which is cyclin D125." (PMID 34083581, 2021). "All of these results indicate that FXR activation inhibits JAK2/STAT3 pathway by regulating SOCS3 transcription in colon cancer cells." (PMID 33164339, 2020). "In order to determine that JAK2/STAT3 signalling is indispensable for the tumour‐suppressive effect of FXR activation on colon cancer cells, colivelin and IL‐6, the agonists of JAK/STAT3 pathway, were adopted to treat FXR‐activated cells." (PMID 33164339, 2020). "For example, Bufalin suppresses cell growth by inhibiting JAK-STAT3 signaling in colon-cancer cells, and convallatoxin promotes apoptosis and inhibits angiogenesis through inhibiting JAK2/STAT3 signaling in colon cancer cells." (PMID 33114727, 2020). "Our data indicated that OCA treatment repressed the activation of JAK2/STAT3 pathway in colon cancer cells, which was further confirmed by IF staining, showing increased levels of STAT3 protein located in the cell cytoplasm." (PMID 33164339, 2020). "In the present study, the FXR agonist OCA inhibited colon cancer cell proliferation and invasion by repressing JAK2/STAT3 pathway via regulating SOCS3 transcription." (PMID 33164339, 2020).
colon carcinoma (continued). "Our immunohistochemical results showed that HBD reduced the expression of JAK2 and P-STAT3 associated with the IL-6/STAT3 signaling pathway and inhibited the formation of tumor cells in colitis-associated colon cancer." (PMID 30832202, 2019). "STAT3, the main downstream target of JAK2, plays an essential role in proliferation and survival in colon cancer-initiating cells." (PMID 30564118, 2018). "On the basis of the evidence presented above, we propose that RAB3C overexpression in colon cancer cells induces IL-6 exocytosis, thereby triggering JAK2 activation and STAT3 phosphorylation and inducing cancer cell metastasis." (PMID 28784136, 2017). "Reducing the expression of JAK2 in colon cancer cells using small interfering RNA (siRNA) decreased AKT expression." (PMID 23426872, 2013). "Reducing the expression of JAK2 in colon cancer cells using JAK2 siRNA decreases the AKT expression levels." (PMID 23426872, 2013). "The present study demonstrated the role of reactive oxygen species (ROS) in the induction of AKT regulation by cisplatin through the activation of JAK2/STAT3 at the transcriptional level in colon cancer cells." (PMID 23426872, 2013). "Recent studies have found that Dihydroergotamine can target colon cancer via JAK2." (PMID 40028162, 2025). "Moreover, α-Hederin was shown to inhibit the proliferation, invasion, and migration of colon cancer cells SW620 by regulating the JAK2/STAT3 signaling pathway." (PMID 38244586, 2024). "It is assumed that the miR-34c-5p/SIRT6/JAK2/STAT3 axis could be an innovative therapeutic target that opens new insights into developing treatment approaches for colon cancer therapy." (PMID 38185635, 2024). "Case-control studies, using more than 1550 patients with colon cancer and 750 cases of rectal cancer, demonstrated that JAK2, SOCS2, STAT1, STAT3, STAT5A, STAT5B, and STAT6 were associated with colon cancer, and that STAT3, STAT4, STAT6, and TYK2 were linked to rectal cancer." (PMID 36982677, 2023). "In addition, radiation treatment can promote the radiation resistance of colon cancer stem cells through the activation of JAK2/STAT3/CCND2 signaling pathway." (PMID 36199626, 2022). "Similarly, overexpression of ZNF460 predicts worse survival and promotes metastasis through JAK2/STAT3 signaling pathway in patients with colon cancer." (PMID 34638319, 2021). "ZNF460 overexpression was significantly associated with poor prognosis and increased metastatic capabilities of human colon cancer by activating JAK2/STAT3 signaling pathway, and ZNF460 might act as a potential prognostic biomarker and therapeutic target." (PMID 33976729, 2021). "Our results indicated that ORI disrupted the JAK2/STAT3 signaling pathway in colon cancer." (PMID 33976735, 2021). "Taken together, these results suggest that FXR activation might suppress JAK2/STAT3 pathway in colon cancer cells by up‐regulating SOCS3 expression." (PMID 33164339, 2020). "Furthermore, we identified numerous CTS transcriptional signatures whose expression was significantly associated with prognosis in colon cancer, such as CEBPB, PPARGC1, STAT3, MTOR, BCL2, JAK2, and CDK1." (PMID 31186640, 2019). "Notably, colon cancer cells can evade JAK2/JAK1-targeted therapy by a reversible shift of the RAS-MEK-ERK pathway activity, which explains the treatment failure of JAK1/2 inhibitors in refractory CRC." (PMID 30670049, 2019). "Here, our additional assays showed that JAK/STAT3 signaling inhibitor AG490 at 50 μM, unlike α-hederin, failed to repress the viability of SW620 cells, suggesting that the JAK2/STAT3 signaling might specifically regulate the EMT of colon cancer cells." (PMID 30363706, 2018).
colon carcinoma (continued). "Fifteen genes (DUSP2, INFGR1, IL6, IRF2, JAK2, MAP3K10, MMP1, NFkB1A, NOS2A, PIK3CA, SEPX1, SMAD3, TLR2, TYK2, and VDR) were associated with colon cancer mortality (PARTP <0.05); JAK2 (PARTP = 0.0086), PIK3CA (PARTP = 0.0098), and SMAD3 (PARTP = 0.0059) had the strongest associations." (PMID 25541970, 2014). "Fifteen genes (DUSP2, INFGR1, IL6, IRF2, JAK2, MAP3K10, MMP1, NFkB1A, NOS2A, PIK3CA, SEPX1, SMAD3, TLR2, TYK2, and VDR) were significantly associated with colon cancer mortality at the <0.05 level; an additional 15 genes had gene PARTP values between 0.05 and 0.10." (PMID 25541970, 2014). "So we examined the phosphorylation of JAK2 (Y1007/1008) in these two colon cancer cell lines." (PMID 20712901, 2010). "In addition, we also provided the first evidence that ZNF460 promoted the invasion and metastasis of colon cancer cells through activating the JAK2/STAT3 signaling pathway and might be a novel therapeutic target in colon cancer." (PMID 33976729, 2021). "Elevated expression of IL‐6 and activation of the JAK2/STAT3 pathway are tightly correlated with the progression of malignancies, including HCC, colon cancer, bc, NSCLC, and NPC." (PMID 41316520, 2025). "α-Hederin was also shown to block the expression of JAK2 or activated STAT3, significantly inhibiting IL-6-induced epithelial-mesenchymal transition in colon cancer cells." (PMID 38244586, 2024). "This compound also inhibits the migration and metastasis of SW620 and human colon cancer cell line (LoVo) cells via down-regulating the expression of COX-2, prostaglandin E2 (PGE2), Janus kinase 2 (JAK2), and STAT3 signaling molecules." (PMID 37560308, 2023). "Anti-IL-6 neutralizing antibody, JAK2 inhibitor and STAT3 gene knockout in mouse cancer cells reduced BMF and BMF-CM induced colon cancer cell spheroid formation." (PMID 36591515, 2022). "In colon cancer, PTK6 interacts with JAK2 and increases STAT3 phosphorylation to enhance stemness and chemoresistance." (PMID 35562900, 2022). "To further explore the mechanism of ZNF460 in promoting the invasion and metastasis of colon cancer, we found that ZNF460 activated JAK2/STAT3 signaling pathway." (PMID 33976729, 2021). "The results showed that downregulation of ZNF460 expression significantly decreased the p-JAK2 and p-STAT3 expression levels in colon cancer cells." (PMID 33976729, 2021). "Colivelin, an agonist of JAK2/STAT3 pathway, antagonized the tumour‐suppressive effect of OCA on colon cancer cells." (PMID 33164339, 2020). "To illustrate the mechanism underlying the regulation of intracellular signal by the Epo and LFM-A13 combination, we investigated the status of the JAK2, AKT, and mitogen-activated protein kinases (MAPK) pathways in colon cancer cells." (PMID 29690619, 2018). "Ruxolitinib, a JAK2 inhibitor, was found to significantly inhibit RAB3C-induced colon cancer cell migration." (PMID 28784136, 2017). "Together these results demonstrate that upon co-culture with cancer cells ADSCs can activate the JAK2/STAT3 pathways in both breast and colon cancer cells via induced IL-6 expression." (PMID 25797257, 2015). "In this study, we identified the JAK2/STAT3 pathway as a key mediator of the resistance to MEK inhibition in K-Ras mutant pancreatic and colon cancer cells." (PMID 25961376, 2015). "Butyrate reduced JAK2 phosphorylation, JAK1 phosphorylation, STAT1 phosphorylation and its nuclear translocation and DNA binding activity in IFN-γ-activated HCT116 or Hke-3 colon carcinoma cell lines." (PMID 35409339, 2022). "Taken together, overexpression of ZNF460 predicted worse survival and promoted metastasis through JAK2/STAT3 signaling pathway in patient with colon cancer, and could be a novel therapeutic target in colon cancer." (PMID 33976729, 2021). "Interestingly, we found that many of the DEGs and their regulators were prognostic markers for colon cancer, including CEBPB, PPARGC1, STAT3, MTOR, BCL2, JAK2, and CDK1." (PMID 31186640, 2019).
colon carcinoma (continued). "In human colon cancer cells, leptin could also promote proliferation and inhibit apoptosis via activation of JNK mitogen activated protein kinase, JAK2 and PI3 kinase/Akt." (PMID 27185268, 2016). "The inhibitory effects of EVO on JAK2/STAT3 signaling and MMP3 expression were stronger than those of AG490, suggesting that EVO is a strong inhibitor of tumor cell migration in colon cancer." (PMID 26580615, 2015). "JAK2 has been shown to be activated in response to a wide variety of stimuli and AG-490 to block induced NOS2 expression in IL-1β/TNFα/IFNγ-stimulated human epithelial-like colon carcinoma DLD-1 cells and in IFNγ/LPS stimulated RAW cells." (PMID 18036230, 2007). "Drug-induced tyrosine phosphorylation of JAK2 and Src attenuated EGFR and STAT3 tyrosine phosphorylation, but EGFR tyrosine kinase inhibitor therapy (gefitinib) suppressed STAT3 phosphorylation in HCT116 colon cancer cells without influencing JAK2 or Src phosphorylation." (PMID 38397437, 2024). "In addition, FTGs activated the AMPK/mTOR autophagy pathway and downregulated the expression of JAK2/STAT3 apoptotic pathway proteins, while upregulated the expression of Bax and caspase-3 proteins and downregulated the expression of Bcl-2 proteins to exert an anti-colon cancer role." (PMID 38202610, 2023). "These transcriptional signatures are mainly involved in immune regulation (CEBPB, STAT3, and JAK2), metabolism (PPARGC1 and MTOR), cell cycle (CDK1), and apoptosis (BCL2), suggesting that the deregulation of these pathways in CTS may contribute to the altered prognosis in colon cancer." (PMID 31186640, 2019).
osteosarcoma (62 papers, 2011 to 2026). A usually aggressive malignant bone-forming mesenchymal neoplasm, predominantly affecting adolescents and young adults. "Meanwhile, FANCD2 knockdown predisposed osteosarcoma cells to ferroptosis by regulating the JAK2/STAT3 pathway." (PMID 36814203, 2023). "miR-19 has also been found to promote the progression of osteosarcoma by targeting and downregulating Socs6 in association with Janus kinase 2 (JAK2)/signal transducer and activator of transcription 3 (STAT3) signaling." (PMID 35126805, 2022). "In this study, we examined the effect of resveratrol on osteosarcoma stem cells and explored the underlying molecular mechanisms of JAK2/STAT3 signaling pathway." (PMID 30356255, 2018). "M2-polarized macrophages can enhance the metastatic potential of osteosarcoma cells by activating Janus kinase (JAK2)/signal transducer and activator of transcription 3 (STAT3) signaling." (PMID 40005151, 2025). "LCP1 has been reported to promote proliferation and metastasis in osteosarcoma cells via the JAK2/STAT3 pathway." (PMID 41044643, 2025). "Of course, the specific mechanism of miR-506-3p in the regulation of JAK2/STAT3 signaling pathway in Doxorubicin-resistant osteosarcoma patients needs to be further investigated." (PMID 38420199, 2024). "In our study, these results indicated that FANCD2 silencing inhibited osteosarcoma cells and tumor growth, as well as promoted ferroptosis by activating JAK2/STAT3 pathway." (PMID 36814203, 2023). "Recently, miR-221-3p derived from M2-polarized TAM exosomes was reported to promote proliferation and metastasis and aggravate the malignancy of osteosarcoma by regulating the SOCS3/JAK2/STAT3 axis." (PMID 37377390, 2023). "Previous research has indicated that piperlongumine inhibits the JAK2/STAT3 pathway to suppress osteosarcoma progression." (PMID 36814203, 2023). "The results showed that TIPE1 specifically decreased the expression level of total STAT3 and p-STAT3 in osteosarcoma cells, instead of the expression of total Jak2 and p-Jak2." (PMID 36151091, 2022). "Western blot results indicate that miR-331-3p affects the occurrence and development of osteosarcoma through the SOCS1/JAK2/STAT3 pathway." (PMID 36199788, 2022). "The Res administration (0–3 μM) decreases cytokine generation and suppresses JAK2/STAT3 axis to impair CSCs features in osteosarcoma via CD133 down-regulation." (PMID 34769099, 2021). "In osteosarcoma cells, IL-6 produced by MSCs activates the JAK2/STAT3 signaling, with the subsequent up-regulation of multidrug resistance protein (MRP) and P-gP expression, which is relevant to poor response rates of clinical osteosarcoma chemotherapy." (PMID 34095111, 2021). "In osteosarcoma cells, curcumin inhibited the p-JAK2/p-STAT3 pathway which was involved in lung metastasis whereas in lung cancer, curcumin suppressed activation of p-STAT3 both in vitro and in vivo." (PMID 34867402, 2021). "It has been suggested that, in osteosarcoma, miR-19a inhibits the JAK2/STAT3 signaling pathway, activates the mitochondrial apoptotic pathway, and promotes the expression of apoptosis-related proteins." (PMID 33504017, 2021). "In conclusion, ML264 inhibits osteosarcoma growth and metastasis by inhibiting the JAK2/STAT3 and Wnt signalling pathways." (PMID 32285603, 2020). "By searching the Ximbio website, three cell lines were additionally recognized in the cell bank: 2C4 gamma1A/JAK2 (fibrosarcoma), S_M6R1 (osteosarcoma), and S_N40R2 (osteosarcoma)." (PMID 30781855, 2019). "Then we performed further investigation on the activity of JAK2/STAT3 signaling pathway in resveratrol treated osteosarcoma cells." (PMID 30356255, 2018). "In this study, we provided evidences that JAK2/STAT3 signaling inhibition was involved in resveratrol induced osteosarcoma stem cells elimination." (PMID 30356255, 2018). "JAK2/STAT3 signaling blockage plays a crucial role in therapeutic effects of resveratrol treated osteosarcoma cells." (PMID 30356255, 2018).